CCL2 (C-C motif chemokine ligand 2)
Diseases named in the same sentence as CCL2 in open-access papers (continued):
Sharing a sentence is not in itself a finding about the gene and the disease.
tumor (continued). "M2-polarized macrophages have been showed to produce large quantities of soluble mediators in the tumor microenvironment such as CCL2, VEGF, and TGF-β1 that interact with neoplastic cells promoting their proliferation and invasion." (PMID 31334111, 2019). "﻿HT-29 or HCT116 cells co-cultured with TAMs exhibited higher expression of CCL2 than tumor cells alone." (PMID 30927925, 2019). "Tumor cell-secreted CCL2 also acts as a monocyte-attracting chemokine to recruit myeloid cells in several metastatic niches." (PMID 31611871, 2019). "In all the studies of this paragraph, CCL2 (secreted from different cell types, being tumor cells and fibroblasts) is involved in priming macrophages to respond to LPS." (PMID 31921102, 2019). "On the other hand, tumor-entrained neutrophils gained activity against 67NR cells when exogenous CCL2 was added to the coculture." (PMID 31921102, 2019). "ASA was further shown to decrease MDSC infiltration, lower the expression of CCL2; and increased influx of CTLs to the tumor site." (PMID 31396227, 2019). "When treated with exosomal Hsp70 and Hsp72, MDSCs was found to significantly increase the production of pro-inflammatory cytokines including IL-6, TNF- α, VEGF, and CCL2, leading to an increase in tumor growth and metastasis." (PMID 31555295, 2019). "Mechanistically, tumor cell-derived CCL2 is critical for the accumulation of monocytes and tumor-associated macrophages (TAMs)." (PMID 31780645, 2019). "Apart from directly influencing tumor and stromal cells and attracting immune cells into the tumor microenvironment, more recently, an additional role in mediating tumor-immune cell crosstalk has been ascribed to CCL2." (PMID 31921102, 2019). "The mRNA expression levels of COX2, TNF-α, Il-6, and Ccl2 were significantly decreased in the tumor tissues of the Ct55 knockout mice compared with those of the WT mice." (PMID 30944312, 2019). "Blockade of CCL2/CCR2 signaling that inhibits tumor-infiltrating macrophages the switch towards a pro-tumor M2 phenotype, suppresses murine liver tumor growth via activating T cell antitumor immune response." (PMID 31572568, 2019). "Accumulated documents indicated that the CCL2/CCR2 axis is an important mediator in the interactions between tumor cells and TAMs." (PMID 31024838, 2019). "In this study, the authors show that incomplete ablation of tumours results in metastases and show in mouse models that the chemokine CCL2 recruits myeloid cells to the partially ablated tumours, which can block T cell function." (PMID 31780645, 2019). "Mechanistically, our in vitro and in vivo study revealed that MAGEA3 has tumor-promoting role by reducing macro-autophagy and overexpressing pro-survival molecules like CCL2 and survivin." (PMID 31287009, 2019). "We subsequently analyzed and found the positive correlation of CTRP1 with tumor-infiltrating macrophages and CCL2 in GBM using TIMER." (PMID 31183364, 2019). "In the tumor microenvironment, the expression of CCL2 respond to pro-inflammatory cytokines or macrophage infiltration." (PMID 31207928, 2019). "S100A4, in a reciprocal manner, activates geminin-overexpressing cells to secrete CCL2 that recruits M0-macrophages from the stroma into the tumor." (PMID 31844158, 2019). "Tumor-derived signals, such as Macrophage-Colony Stimulating Factor (M-CSF/CSF-1), Monocyte Chemoattractant Protein-1 (MCP-1), or Chemokine (C-C motif) Ligand-2 (CCL2) entails the accumulation of M2 at the tumor site." (PMID 31480382, 2019). "Recently, it has been shown that the CCL2 expression level correlates with the recruitment of monocytes/macrophages into tumor tissues." (PMID 31207928, 2019). "Cancer cells can secrete leukocyte attracting chemokines, such as C-C Motif Chemokine Ligand 2 (CCL2), CCL4, CCL5, CCL7, CCL8, and CCL20 leading to an infiltration of tumor associated macrophages, neutrophils, T cells, and dendritic cells." (PMID 31174326, 2019).
tumor (continued). "These three papers suggest an interplay between CCL2 and monocytes that leads to decreased tumor cell growth." (PMID 31921102, 2019). "The authors also proved that this antitumor response was CD8+ T cell-dependent, and that PLX4032 also decreased CCL2 expression in tumor microenvironment in this model." (PMID 31134073, 2019). "It is demonstrated that CCL2 induces EMT process dependent on the activation of STAT3 signal and p-STAT3 inhibition suppresses CCL2 expression, leading to reduced invasiveness of tumor cells." (PMID 31182136, 2019). "CCL2 is expressed by cancer and stromal cells in the tumor microenvironment and promotes tumor cell proliferation at the primary tumor site and tumor cell migration and invasion into the surrounding extracellular matrix." (PMID 30871117, 2019). "CCL2 is a major driver of macrophage infiltration and has been shown to promote tumor progression in several cancer models." (PMID 30651598, 2019). "In vivo, TAMs from KEP tumors of CCL2-blocking antibody-treated mice showed significantly decreased IL-1β mRNA expression vs. control KEP tumor-bearing mice." (PMID 31921102, 2019). "In another study, the effect of tumor-derived CCL2 was investigated by incubating macrophages (derived from THP-1 cells by PMA treatment) with conditioned medium of the salivary adenoid cystic carcinoma cell line SACC-83." (PMID 31921102, 2019). "Local radiation of tumor-bearing mice resulted in tumor cell production of the type 1 interferon IFNβ which, in turn, induced CCL2, CCL7, and CCL12 and chemoattracted CCR2+ M-MDSC to the tumor microenvironment." (PMID 31001479, 2019). "CXCL9 and CCL2 stood out as chemokines described to be critical for CD8+ T cell tumor infiltration, and the recruitment of TAMs and Tregs15–17, respectively." (PMID 31186412, 2019). "Increased tumor incidences in Brg1IEC-AKO mice were associated with the persistent inflammation, as reflected by increased IL-6, IL-1β, TNFα and CCL2 productions in the 5 months of AOM-treated Brg1IEC-AKO mice." (PMID 31601814, 2019). "Peripheral microglia are attracted and recruited inside the tumor core by the secreted factors released from the tumor cells like CCL2, CSF1, or EGF." (PMID 31824268, 2019). "Nitrosylation of CCL2, which normally supports tumor-infiltrating lymphocyte trafficking into the tumor core, occurs through the production of reactive nitrogen species in the TME." (PMID 30828330, 2019). "Apart from monocytes and macrophages, also neutrophils have been investigated in the context of influencing tumor progression in the presence of CCL2." (PMID 31921102, 2019). "Accumulated studies indicated that CCL2 promoted the recruitment of TAMs via activating its receptor CCR2 in the process of tumor invasion and metastasis." (PMID 31024838, 2019). "Multiple studies describe an important role of CCL2 in the tumor microenvironment in different types of cancer." (PMID 31921102, 2019). "We demonstrated that the inhibition of CCL2 blocked macrophage recruitment and angiogenesis, which resulted in decreased tumor volume and blood volume in CCL2-expressing GBM in a rat model." (PMID 31366997, 2019). "For this in vivo study, bevacizumab (20 mg/kg, twice/week) with or without mNOX-E36 (20 mg/kg, 4 times/week) was administered intraperitoneally to CCL2-expressing U87 MG tumor-bearing rats after undergoing a pretreatment MRI." (PMID 31366997, 2019). "It is clear, however, that the role of CCL2 in tumorigenesis is likely to be affected by tumor-specific factors." (PMID 31823764, 2019). "During cancer metastasis, CCL2 promotes tumor cell intravasation into the circulation, likely by recruiting host myeloid cells to facilitate this process." (PMID 30871117, 2019). "Work by Peng's group showed that tumor-derived fibroblasts secreted MCP-1 (known as CCL2), the ligand for CCR2 or CCR4, and RANTES (known as CCL5), the ligand for CCR1, CCR3, or CCR5." (PMID 30800130, 2019).
tumor (continued). "Exosomes released from MM patients' BM-MSC modulate disease progression in vivo by increasing the exosome-based delivery of IL-6, CCL2 (C-C motif chemokine ligand 2), and fibronectin and decreasing expression of the tumor suppressor miR-15a." (PMID 31281380, 2019). "CCL2 can also derive from tumor cells undergoing EMT (e.g., through ZEB1), promoting M2 polarization." (PMID 31416205, 2019). "CAF contribute to shape the immune cells in tumors by secreting proinflammatory cytokines and chemokines, notably TGFβ, IL-6 and CCL2, to recruit immunosuppressive cells into the tumor stroma and reject effector T cells." (PMID 30871158, 2019). "Once tumor cells migrate and colonize the distant sites, they release CCL2 which further recruits inflammatory monocytes and convert them into metastasis-associated macrophages." (PMID 30925924, 2019). "Apart from CCL2, there are certain other chemokine attractants exuded by the tumor mass such as CCL5, CXCL8, CCL7 and CXCL12 and a few other cytokines like VEGF and M-CSF." (PMID 30925924, 2019). "Diverse cytokines and factors, including VEGF, granulocyte-macrophage colony stimulating factor (GM-CSF), IL-6, IL-10, TGF-β, interferon (IFN)-γ, IL-1β, and CCL2, are main attractors of MDSCs toward tumor tissue and affect their activation." (PMID 31484464, 2019). "In vitro, CCL2 was shown to induce killing of cultured MDA-MB231 tumor cells by human neutrophils added as suspension in the presence of granulocyte-CSF (G-CSF)." (PMID 31921102, 2019). "Chemotactic cytokines released from a tumor microenvironment i.e. CCL2, CXCL1, CXCL10, PGE2, histamine, VEGF, angiopoietin 1 (Ang1), CXCL8/IL-8 attract mast cells from the vicinity and recruit them from circulation." (PMID 30680411, 2019). "Blockade of the CCL2/CCR2 axis has exhibited efficacy in TAMs-related therapy with several preclinical tumor models." (PMID 31024838, 2019). "CCL2 expression was reduced by treatment with Foretinib and Bay-117082, consistent with the observed reduction in tumor macrophages." (PMID 31903163, 2019). "For instance, RET/PTC induces the expression of oncogenes involved in inflammation and tumor invasion, such as chemokines (CCL2, CCL20, CXCL8/IL-8, and CXCL12), chemokine receptor CXCR4, and cytokines (IL-1B, colony-stimulating factor 1, and GM-CSF)." (PMID 31500315, 2019). "The elevations in CXCL8 and CCL2 expression partly depended on direct physical contacts between the tumor cells and the MSCs/CAFs, whereas CCL5 up-regulation was entirely dependent on cell-to-cell contacts." (PMID 31031757, 2019). "Macrophages are the effector cells of the innate immune system and express C-C chemokine receptor type 2 (CCR2) in response to CCL2 resulting in continuous recruitment of macrophages to the tumor sites." (PMID 31660078, 2019). "CCL-2 inhibition reduces tumor growth and metastasis in preclinical models, when administered in combination with chemotherapy, neutralization of CCL-2 improved the efficacy of treatment." (PMID 31805946, 2019). "Tumor-secreted CCL2 signals through the CCR2 receptor expressed on TAMs and result in release of IL-6 to promote glioma cell invasiveness." (PMID 31611871, 2019). "Discontinuation of CCL2 therapy accelerates breast cancer metastasis by promoting tumor angiogenesis." (PMID 30823602, 2019). "A blockade of CCL2 with specific antibodies in mice models showed inhibition of tumor growth, again together with the lower number of TAM." (PMID 30680411, 2019). "M-MDSC were shown to accumulate in tumor via CCL2-dependent mechanisms, whereas PMN-MDSC accumulate in a CXCL8-depenent manner." (PMID 30936876, 2019). "Adding back exogenous CCL2 by intratumoral injection led to an increase in tumor burden and tumoral MDSC accumulation." (PMID 31921102, 2019). "The findings were confirmed in vivo, where CCL2-positive tumor cells produced significantly fewer lung metastases." (PMID 31921102, 2019).
tumor (continued). "We observe that the blockade of LIF in tumors expressing high levels of LIF decreases CD206, CD163 and CCL2 and induces CXCL9 expression in tumor-associated macrophages." (PMID 31186412, 2019). "In contrast, peripheral CCL2 significantly decreased in mice treated with cRFA as comparing to iRFA and untreated-mice, suggesting the increase of CCL2 is originated from the residual tumor." (PMID 31780645, 2019). "Blocking CCL2 signalling reduced the TRAIL-induced tumour-supportive immune microenvironment and tumour growth." (PMID 31010082, 2019). "CCL2 and CCL5 induce tumor-associated macrophages (TAMs), thereby inhibiting T-cell activation and promoting angiogenesis in breast tumors." (PMID 31398937, 2019). "Monocytes from the blood stream are attracted to tumour tissue through a gradient of CCL2 cytokine released by the TME." (PMID 31160587, 2019). "It has been observed that TANs actively communicate with tumor cells through growth factors or inflammatory cytokines such as TNFα, CCL2, IL-8, and IL-17a, which can promote tumorigenesis and progression." (PMID 30616627, 2019). "More evidence also points toward an involvement of the CCL2/CCR2 axis in the crosstalk between tumor cells and macrophages leading to immunosuppression." (PMID 31921102, 2019). "A recent report indicated that it is highly secreted by fibrosarcoma tumor cells; in addition, ectopic expression of IL-17D in tumor cells recruits natural killer cells via the CCL2 production of endothelial cells." (PMID 31244826, 2019). "LPS stimulation of tumor hepatocytes further enhanced the expression of inflammatory cytokines and chemokines Ccl2, Cxcl1, Cxcl2, Tnfa, and Il6." (PMID 30990169, 2019). "Immunohistochemical staining revealed that both Klotho and CCL2 are expressed primarily in the stroma of the tumor tissue." (PMID 31545552, 2019). "Mimicking the effects of flagellin on cultured CRC cells, both IL6 and CCL2 were significantly increased in murine C26 cancer tumors when compared with the C26 tumor cells from which the C26 tumors originated." (PMID 31731747, 2019). "CCL2 interaction with its cognate receptor CCR2 promotes PCa tumour growth by sustaining macrophage infiltration and angiogenesis." (PMID 31718684, 2019). "Low levels of CCL2 led to modest macrophage infiltration and tumor formation by promoting angiogenesis, whilst higher levels were associated with increased macrophage infiltration and tumor regression." (PMID 30899263, 2019). "Taken together, tumor cells derived-CCL2 signal plays a vital role in promoting the infiltration of monocytes and differentiation into TAMs, resulting in high invasiveness of the residual tumor." (PMID 31780645, 2019). "Use of anti-CCL2 antibodies selectively restrains radiotherapy-dependent recruitment of classical monocytes, impeding tumor progression when combined with radiotherapy." (PMID 31474975, 2019). "The migration of macrophages among CCL2-expressing tumor cells decreased after mNOX-E36 (400 μg/mL) treatment compared to that of vehicle treatment [(U87 MG (p = 0.0075) and LN 18 (p = 0.0021)]." (PMID 31366997, 2019). "Because CCL2 has an important role in tumor progression and metastasis, this chemokine was identified as a potential therapeutic target in cancer." (PMID 31762942, 2019). "In response to high expression levels of CCL2 in tumor microenvironment, LM-Dox exhibit tumor tropism and subsequently hijack the established tumor microtubes of lung tumor cells to selectively deliver the chemotherapeutic drugs." (PMID 31660078, 2019). "In an in vivo study, bevacizumab (20 mg/kg, twice/a week) with or without mNOX-E36 (20 mg/kg, 4 times/a week) was administered intraperitoneally to CCL2-expressing U87 MG tumor-bearing rats after performing a pretreatment MRI." (PMID 31366997, 2019). "Subsequently, the infiltrating macrophages promoted the residual tumor cells to produce CCL2 through TNFα." (PMID 31780645, 2019).
tumor (continued). "We found that several neutrophil-attractant molecules and the monocyte chemo-attractant protein 1 (MCP1, CCL2) were highly expressed in tumours." (PMID 31160587, 2019). "Tumor-derived CCL2/5 are significant indicators of early relapse and infiltration of TAMs, which contribute to cancer cell proliferation, inflammatory microenvironment of tumors, immune response evasion and angiogenesis." (PMID 31331345, 2019). "CCL2 is reported to increase bone metastasis through recruitment of TAMs and osteoclasts to the tumor site and blood vessel formation through vascular endothelial growth factor-A." (PMID 30871130, 2019). "To analyze the effect of CCL2 inhibition, we used mNOX-E36 as a CCL2 inhibitor in CCL2-expressing tumor cells." (PMID 31366997, 2019). "In this mechanism, CCL2 is nitrated or nitrosylated by RNS such as peroxynitrite in the tumor environment." (PMID 31225500, 2019). "They found the expression of CCL2/CCL20 was significantly increased in lung cell fraction containing both tumor and lung cells." (PMID 30800130, 2019). "The vascular disrupting agent combretastatin A4-P causes the increased production of CSF-1, CCL2, and CXCL12 that increases monocyte recruitment and TAM accumulation in tumor sites." (PMID 32038607, 2019). "Collectively, these data suggested that targeting CCL2/CCR2 enhanced anti-tumor immunity in the residual tumor, thereby overcoming the resistance to immune checkpoint blockade therapy." (PMID 31780645, 2019). "CCR2 inhibitors and anti-CCL2 antibodies have shown efficacy in reducing tumor growth and metastasis in several pre-clinical murine models." (PMID 31878087, 2019). "TAMs are recruited to the tumor microenvironment commonly by tumor-derived cytokines and chemokines, including CCL2, VEGF, M-CSF, and TGF-β." (PMID 30894684, 2019). "Further work from the same group indicates that a CD40 agonist triggers the release of IFNγ and CCL2 responsible for both the recruitment of monocytes/macrophages into the tumor and their polarization toward ECM-degrading cells." (PMID 31354719, 2019). "CCL2 is a potent chemokine that regulates the migration of immune cells to tumours through the recognition of CCR2 receptors." (PMID 31535788, 2019). "FoxQ1 inhibition via miR-506-3p and subsequent CCL2 upregulation can promote circulating tumor cell (CTC)-mediated tumor metastasis in CRC patients." (PMID 31887997, 2019). "Inflammatory monocytes are rapidly recruited at sites of tumor growth, following specific signaling by chemokines (e.g., CCL2), but also CSF-1, cytokines, or complement components (C5a)." (PMID 31878087, 2019). "CCL2 promotes tumor growth and tumor colonization at metastatic sites by recruiting additional myeloid and endothelial cells." (PMID 30871117, 2019). "During neoplastic transformation, the tumor cells start expressing C-C motif chemokine ligand 2 (CCL2), which is the major chemoattractant of monocytes and macrophages." (PMID 30925924, 2019). "Further, we showed anti-PD-1 mAb was effective to inhibit the growth of the residual CCL2 knock out tumor." (PMID 31780645, 2019). "N2 neutrophils are characterized as a higher expression of pro-tumor factors to induce the immunosuppression in the tumor microenvironment, including CCL2, CCL5, neutrophil elastase (NE), and cathepsin G (CG), with a higher expression of arginase." (PMID 31010242, 2019). "Low expression of Klotho, or high expression of CCL2 in patient tumor tissues, correlated with poor overall survival of CRC patients." (PMID 31545552, 2019). "In the tumor microenvironment, CCL2 can be produced and secreted into the extracellular environment by many cells, such as cancer cells, fibroblasts, tumor-infiltrating monocytes, and endothelial cells." (PMID 31500658, 2019). "Here, we showed that CCL2 expression resulted in enhanced tumor growth with increased resistance to bevacizumab in a rat GBM model." (PMID 31366997, 2019).